PARP1 (poly(ADP-ribose) polymerase 1)
Diseases named in the same sentence as PARP1 in open-access papers (continued):
Sharing a sentence is not in itself a finding about the gene and the disease.
oral cancer (18 papers, 2012 to 2025). "PARP1 is known to have high expression levels in oral cancer and hence a more than 30% mutation frequency in our data, suggests an activating mutation in all tumor sites." (PMID 34796107, 2021). "It is overexpressed in recurrent oral cancer, leading to high resistance of tumor cells to DNA damage therapies, indicating that PARP1 is part of a protective mechanism in cancer cells." (PMID 40303286, 2025). "PAC (3,5‐Bis (4‐hydroxy‐3‐methoxybenzylidene)‐N‐methyl‐4‐piperidone) is recently reported to reduce cell survival through promote apoptosis and autophagy by activating NF‐κB, MAPK, Wnt, caspase‐3/9 and PARP1 at the dose of 5 μM in oral cancer CA9‐22 cells." (PMID 35191177, 2022). "Our results showed that anethole is triggering cell death in oral cancer cells through induction of caspase 3 and PARP-1 active forms." (PMID 34158560, 2021). "In this study, we revealed upregulation of PARP1 as a mechanism that rendered oral cancer cells resistant to treatment, and PARPi as effective agents that re-sensitized these cells to chemotherapy in vitro and in vivo." (PMID 35071239, 2021). "Upon treatment with cisplatin and 5-FU, two chemotherapeutic drugs used for oral cancer, PARP1 expression was further increased in SCC11B, by approximately 50 and 100%, respectively." (PMID 35071239, 2021). "In this study, the PARP-1 inhibitor AZD2281 showed in vitro synergetic effects in combination with cisplatin in three cell lines derived from oral carcinoma, HSC-2, Ca9-22 and SAS, and partly in vivo synergetic effects in xenografted HSC-2 tumors." (PMID 26927065, 2016). "Here, we aimed to establish a molecular imaging approach using rapid PARP1 targeted fluorescence imaging to yield a reproducible measure of the effects of external beam radiation to oral cancer tissue." (PMID 26808835, 2016). "Collectively, our results suggest that PARP1 imaging with PARPi-FL can enhance the detection of oral cancer, serve as a screening tool and help to guide surgical resections." (PMID 26900125, 2016). "Additionally, PARP1 overexpression has also been observed in recurrent oral cancers that have developed resistance to chemotherapy and radiation, linking PARP1 function to progressed malignancies." (PMID 40149342, 2025). "Also, our results demonstrate that PAC strongly induces oral cancer cell apoptosis mediated via the mitochondrial pathway by increasing the Bax/Bcl-2 protein expression ratios, activating caspase-3/9 and cleaving PARP-1." (PMID 34083581, 2021). "Thus, the physiological relevance of PARP1 in oral cancer recurrence provides an additional rationale for PARP1 targeting." (PMID 35071239, 2021). "Intraoperative visualization of PARP1 could potentially lead to sensitive and specific imaging of oral cancer, helping clinicians to assess surgical margins in real time." (PMID 32636416, 2020). "We show that PARP1 expression in oral cancer is high, and that the uptake of PARPi-FL is selective, irrespective of whether cells were exposed to irradiation or not." (PMID 26808835, 2016). "Hence, PARP1 imaging could result in earlier detection of oral cancer and reduce the morbidity of radical surgery that plagues patients suffering from OSCC." (PMID 26900125, 2016). "We previously demonstrated that a simultaneous overexpression of PARP-1 and CAF-1/p60 was a still more reliable prognosticator of poor outcome compared to CAF-1/p60 alone in oral carcinoma." (PMID 33098490, 2021). "Furthermore, we noted a similar fashion of 5-FU-induced PARP1 upregulation in SCC10B, another oral cancer cell line derived from recurrent tumor." (PMID 35071239, 2021). "The effect of PAC of caspase signaling for oral cancer cell apoptosis was confirmed by Western blotting showing that PAC at 5 μM strongly decreases Bcl-2 expression and increases that of pro-apoptotic Bax and cytochrome C as well as allows cleavage of PARP-1." (PMID 34083581, 2021).
oral cancer (continued). "Here, we show that PARP1 is overexpressed in oral cancer, and using this model, we determine that PARPi-FL is a selective marker in oral cancer cell lines, irrespective of whether they received ionizing radiation or not." (PMID 26808835, 2016).
sarcoma (18 papers, 2008 to 2025). A usually aggressive malignant neoplasm of the soft tissue or bone. "Radiation therapy has been studied separately both in association with trabectedin in sarcomas, at the preclinical and clinical level, and with PARP1-inhibitors, which are known radiosensitizers." (PMID 34944915, 2021). "Fused in sarcoma (FUS) is involved in the formation of nuclear biomolecular condensates associated with poly(ADP-ribose) [PAR] synthesis catalyzed by a DNA damage sensor such as PARP1." (PMID 39596510, 2024). "A prior study found that the expression of PARP1, γH2AX, BRCA1, and BRCA2 was associated with shorter survival of patients with sarcoma." (PMID 40563612, 2025). "In our L-sarcoma lines, increased apoptosis was observed by both flow cytometry and PARP-1 and caspase-3 processing which would explain the synergy observed only in the LPS line." (PMID 36614121, 2022). "In search of clinically feasible PARP1i partners, we and others showed that the antitumor activity of trabectedin was increased by PARP1 inhibition in sarcoma preclinical models." (PMID 34944915, 2021). "In fact, we recently demonstrated that PARP1 inhibition enhances trabectedin-induced DNA damage and that treatment with this combination is feasible and active in advanced sarcoma patients." (PMID 34944915, 2021). "We previously showed that PARP1 inhibition perpetuates the DNA damage induced by the chemotherapeutic agent trabectedin in both preclinical models and sarcoma patients." (PMID 34944915, 2021). "This was reflected in decreased incidence of late occurring tumors, including sarcomas and other tumors, with exception of Parp-1-/-/Ptc1+/- mice, in which MB mortality was already high and did not significantly increase with irradiation." (PMID 29254138, 2017). "Additionally, we demonstrated that the combination of the alkylating agent trabectedin and the poly (ADP-ribose) polymerase-1 (PARP1) inhibitor olaparib exhibits antitumor activity against a subset of sarcomas in both preclinical and clinical studies." (PMID 40986050, 2025). "Moreover, we studied the antitumor activity of the alkylating agents trabectedin and the PARP1 inhibitor olaparib, observing variable degrees of synergism against advanced sarcomas in preclinical and clinical settings." (PMID 40986050, 2025). "Noteworthy, PARP3 seems to be overexpressed in tumors that benefit from trabectedin treatment (i.e., L‐sarcomas and tumors with somatic location), while PARP1 expression is higher in sarcomas with lower activity of trabectedin (non‐L‐sarcomas and tumors with visceral location)." (PMID 33983674, 2021). "Because of that, the cleavage of caspase-3 and PARP1 was determined in both sarcoma cell lines." (PMID 34540832, 2021). "Next, we pursued PARP1 inhibition with olaparib to potentiate the antitumor effect of DNA damaging effect of the DNA damaging agent doxorubicin to achieve an optimal synergy in sarcoma." (PMID 32963243, 2020). "In undifferentiated sarcomas, none clinicopathological prognostic variable was associated with the PARP1‐based classification that was itself associated with MFS." (PMID 31131495, 2019). "The alkylating agent trabectedin, when combined with the poly (ADP-ribose) polymerase 1 (PARP1) inhibitor olaparib, exhibits variable antitumor effects in advanced sarcomas." (PMID 40986050, 2025). "We evaluated PARP1/2 and WEE1 inhibition ex vivo in patient-derived sarcoma cell models as monotherapy and in combination with chemotherapeutic agents to identify synergistic effects." (PMID 39535612, 2024). "Immunohistochemistry score of intensity for PARP1, BRCA1, and RAD51 protein expression in formalin-fixed paraffin-embedded sarcoma samples." (PMID 28454547, 2017). "We employed immunohistochemistry (IHC) to measure PARP1, BRCA1, and RAD51 expression in a panel of 54 patient-derived sarcoma specimens." (PMID 28454547, 2017).
sarcoma (continued). "PARP3 and PMS1, which were genes associated with a better PFS of trabectedin, were overexpressed in L‐sarcomas and in tumors with a somatic location, whereas PARP1, a gene that correlated with worse PFS of trabectedin, was highly expressed in non‐L‐sarcomas and tumors with visceral location." (PMID 33983674, 2021). "The most frequent tumors were nonepithelial uterine tumors (mostly polymorphic sarcomas, as well as vascular tumors, namely, cavernoushemangiomas and hemangiendotheliomas) both in PARP-1−/− and PARP-1+/+ mice." (PMID 19415146, 2008). "Furthermore, PARP1 regulates NHEJ (Non-homologous end joining), and its inhibitors, such as olaparib, also cause DNA damage and are used in sarcomas in combination with DNA damaging agents, such as ionizing radiation (IR)." (PMID 34540832, 2021).
ischemic stroke (17 papers, 2010 to 2025). A stroke disorder caused by obstruction of blood flow to the brain, due to thrombotic (local blood clot formation) or embolic (due to a blood clot or other material traveling from another site) event. "We further aimed to identify key mediators underlying the actions of PARP-1 inhibitor in the ischemic stroke." (PMID 32317937, 2020). "Much effort has been paid to explore the detailed mechanisms underlying the actions of PARP-1 in modulating cell apoptosis, necrosis, and inflammation after ischemic stroke." (PMID 32317937, 2020). "PARP-1 activation has also been linked to Alzheimer’s (AD), Parkinson’s (PD) and ischemic stroke, and the use of PARP-1/2 inhibitors is beneficial to mouse models of these diseases." (PMID 30157956, 2018). "Further, we conducted PPI network analysis on significant genes, identifying core networks involving PARP1 for epilepsy, MCL1 for VaD, and connections between these and other proteins associated with ischemic stroke." (PMID 40624693, 2025). "The PPI network analysis revealed significant associations between PARP1, MCL1, and CD40, highlighting potential common pathways involved in ischemic stroke, epilepsy, and VaD." (PMID 40624693, 2025). "The depletion of NAD+ after ischemic stroke can lead to cell death and is associated with the excessive activation of poly-ADP-ribose polymerase (PARP1), as well as an increase in the CD38 enzyme, which consumes NAD+." (PMID 39795876, 2024). "JPI-289, a recently developed novel PARP-1 inhibitor with potent PARP-1 inhibitory activity, revealed beneficial effects in ischemic stroke models." (PMID 38167603, 2024). "JPI-289 (also called amelparib), a PARP1 inhibitor, has also shown effective neuroprotection in experimental models of ischemic stroke in vivo and in vitro." (PMID 38026442, 2023). "In the female group, complement and coagulation cascades, ECM-receptor interaction, and IL-17 signaling pathways were significantly influenced by delayed treatment of PARP-1 inhibitor in the ischemic stroke." (PMID 32317937, 2020). "Recent evidence suggests that poly (ADP-ribose) polymerase (PARP)-1 inhibitor exerts sex-specific neuroprotection in the ischemic stroke." (PMID 32317937, 2020). "Accumulating evidence reveals that excessive activation of PARP-1 contribute to pathogenesis of many diseases including ischemic stroke." (PMID 32317937, 2020). "In ischemic stroke, cell death occurs via a poly(ADP-ribose) polymerase-1 (PARP)-dependent pathway leading to AIF release from the mitochondria andParthanatos18,19." (PMID 29250322, 2017). "The interaction between PARP1 and MCL1 suggests that PARP1 may regulate cell survival pathways, potentially influencing the neuroinflammatory processes observed in neurovascular diseases, including ischemic stroke and VaD." (PMID 40624693, 2025). "We further proposed that Prx1 might be a critical factor involved in the actions of PARP-1 inhibitor in both males and females in the ischemic stroke." (PMID 32317937, 2020). "Although acute PARP-1 and MMP inhibition may effectively attenuate ischemic stroke, the roles of MMPs in neuronal progenitor migration, and PARP-1's role in angiogenesis programs during restitution need some clarification." (PMID 21176168, 2010). "Therefore, PARP-1 inhibitors hold promise in clinical treatment for ischemic stroke." (PMID 32317937, 2020). "JPI-289, a recently developed novel PARP-1 inhibitor with strong PARP-1 inhibitory activity, showed beneficial effects in ischemic stroke models." (PMID 33178190, 2020). "Poly (ADP-ribose) polymerase-1 (PARP-1), an NAD+ consuming enzyme, is overactivated in ischemic stroke and has been shown to play a dominant role in neuronal death after ischemic stroke." (PMID 25387075, 2014).
ischemic stroke (continued). "Ischemia/reperfusion has been shown to lead to elevated matrix metalloproteinase activity, which further promoted (i) the degradation of the two important DNA repair proteins poly-ADP ribose polymerase 1 (PARP1) and XRCC1 and (ii) the accumulation of oxidative DNA damage after an ischemic stroke." (PMID 23203191, 2012).
colitis (16 papers, 2009 to 2026). Inflammation of the colon. "Colitis: PARP2 deficiency in T cells → (↓TNFα/IL‐17 + ↓oxidative stress/PARP1 activation) → suppresses intestinal inflammation." (PMID 40904702, 2025). "Results showed that PARP1−/− mice develop less severe colitis than WT mice, as shown by decreased weight loss (* p < 0.05), a higher clinical score value (* p < 0.05) and an increased colon length (** p < 0.01)." (PMID 37108260, 2023). "It has been previously reported that genetic deficiency or pharmacological inhibition of PARP-1 confers beneficial effects in experimental models of colitis." (PMID 20204057, 2009). "After restoring Stc1 and Parp1, Stc1INT‐KO mice with DSS‐induced colitis exhibited increased weight loss, shorter colons, higher DAI scores, more histological damage in the colonic epithelium, and higher histological scores." (PMID 38088577, 2024). "Restoring Stc1 and Parp1 in vivo also led to more severe colonic mucosal damage during colonoscopy and higher endoscopic colitis scores." (PMID 38088577, 2024). "Results show that PARP1−/− mice develop less severe colitis than WT mice, evidenced by a significant decrease in fecal and serum HMGB1, and, similarly, treating WT mice with PJ34 reduces the secreted HMGB1." (PMID 37108260, 2023). "We found that PARP1−/− mice show less severe colitis highlighted by improved clinical parameters as well as by significantly reduced amounts of serum and fecal HMGB1." (PMID 37108260, 2023). "Oxidative damage during the pathogenesis of IBD is known to promote structural alterations in DNA, and PARP1 activation has been shown to be increased within the intestinal mucosa of mice subjected to experimental colitis and in humans with UC." (PMID 37744380, 2023). "In sum, after treatment with DSS, PARP1−/− mice show less severe colitis compared to wild type mice, as evidenced by the significantly reduced amounts of serum and fecal HMGB1." (PMID 37108260, 2023). "Previous studies showed elevated PARP1 activity in the inflamed colon of the chemically and genetically induced colitis animal models with an increased level of mucosal protein PARylation or ex vivo enzyme activity." (PMID 37457706, 2023). "Accordingly, PARP-1−/− mice were protected in 2,4,6-trinitrobenzene sulphonic acid- (TNBS-) induced colitis and pharmacological inhibitors of PARP-1 improved dextran sodium sulfate-induced and TNBS-induced colitis in rodents." (PMID 34567413, 2021). "As for PARP1, a murine experimental model of colitis shows the contribution of PARG in sustaining the inflammatory response in the colon." (PMID 30991935, 2019). "Western blot analysis demonstrated a marked PARP-1 proteolysis in rats with experimental colitis, which was significantly lower in the groups of TNBS-treated rats which received glutamine." (PMID 23209735, 2012). "We compared the expression of PARP-1 in rats subjected to TNBS-induced colitis and colitic rats treated with glutamine." (PMID 23209735, 2012). "The recent studies in a variety of rodent models of experimental colitis support the role of PARP-1 activation in the pathogenesis of the disease." (PMID 20204057, 2009). "Finally, following restoration of Stc1 and Parp1 expression by adeno‐associated viruses, and overexpression of Stc1 and Parp1 aggravated DSS‐induced colitis in Stc1INT‐KO mice." (PMID 38088577, 2024). "In contrast, restoring Stc1 and Parp1 in vivo aggravated murine colitis." (PMID 38088577, 2024). "PJ34 reduces intestinal inflammation in mice with DSS colitis by inhibiting PARP1." (PMID 37371959, 2023). "Furthermore, enhanced PARP-1 expression was found in the colon of rodents in experimental colitis models, as well as in IBD patients, which makes the model more valuable for studying PARP inhibitors." (PMID 34567413, 2021).